VCP (valosin containing protein)
Diseases named in the same sentence as VCP in open-access papers (continued):
Sharing a sentence is not in itself a finding about the gene and the disease.
neurodegenerative disease (64 papers, 2010 to 2026). A disorder of the central nervous system characterized by gradual and progressive loss of neural tissue and neurologic function. "A series of nine pathogenic mutations in valosin-containing protein (VCP), which is associated with neurodegenerative diseases including ALS, were generated by CRISPR/Cas9 in the fruit fly, and both sexes were examined in each case." (PMID 38450661, 2024). "VCP harbors dominant mutations that underlie two neurodegenerative diseases, multisystem proteinopathy and vacuolar tauopathy, but its mechanistic role is unclear." (PMID 38826306, 2024). "VCP is implicated in a broad spectrum of health conditions that include several neurodegenerative diseases." (PMID 37545006, 2023). "Nevertheless, further studies are required to elucidate and compare the SG-recruitment kinetics of these late modules—i.e., the proteasome and VCP—under different stress conditions and in the context of neurodegenerative disease-linked mutations." (PMID 38012130, 2023). "Despite solid evidence linking VCP mutations to neurodegenerative diseases, it should be emphasized that their pathologies and the properties of intracellular aggregates vary widely." (PMID 37545006, 2023). "To date, the published work suggests that the contributions of VCP mutations to neurodegenerative disease depend on the characteristics of the patient cohort." (PMID 37545006, 2023). "Support for the physiological relevance of VCP in antagonizing amyloid aggregation is provided by mutations in VCP that are associated with the deposition of ubiquitylated aggregates in neurodegenerative diseases such as vacuolar tauopathy and IBMPFD21,29,61." (PMID 36732333, 2023). "VCP mutations are causative of multisystem proteinopathies, which include neurodegenerative diseases (NDs), and share various signs of altered proteostasis, mainly associated with autophagy malfunctioning." (PMID 35216053, 2022). "Many studied reported that more than 50 missense mutations in gene coding VCP is causative in many neurodegenerative diseases characterised by ALS, FTD, IBM, CMT2Y, and PBD." (PMID 34918006, 2022). "We link SVIP to VCP-dependent degenerative disease through phenotypic analysis of a known human disease-causing mutation in Drosophila VCP, and we present the identification of an SVIP mutation in a human patient diagnosed with fronto-temporal dementia (FTD)." (PMID 33479240, 2021). "VCP/p97 mutations have been associated with a multisystem degenerative disease that comprises Paget's disease of bone, inclusion body myopathy, and fronto-temporal dementia (IBMPFD), and with several other diseases of the nervous and muscular system." (PMID 30153561, 2018). "Histopathological analysis of VCP-associated neurodegenerative diseases show that affected tissues contain prominent inclusions containing ubiquitin and TDP-43, and an accumulation of LC3 and p62." (PMID 29282133, 2017). "Loss-of-function mutations in VCP are linked to several human degenerative diseases, including inclusion body myopathy (IBM), ALS-FTD." (PMID 29282133, 2017). "Mutations in a gene that produces a protein called Valosin-containing protein (VCP for short) causes degenerative diseases that affect the brain, muscle and bone." (PMID 26167652, 2015). "All of these phenotypes are hallmarks of degenerative diseases that are associated with mutations in VCP." (PMID 26167652, 2015). "ALS is a neurodegenerative disease involving both upper and lower motor neurons, and is caused by VCP gene mutations in up to 2–3% of isolated familial ALS." (PMID 23029473, 2012). "The links between VCP mutations and neurodegenerative diseases are well-established." (PMID 37545006, 2023). "More than 45 missense mutations in VCP have been identified in multiple neurodegenerative diseases." (PMID 36196920, 2022). "Valosin-Containing Protein (VCP) is linked to diverse degenerative diseases." (PMID 33479240, 2021).
neurodegenerative disease (continued). "Mutations in BAG3 and VCP genes are responsible for late onset degenerative diseases affecting skeletal muscle, suggesting that these proteins might play an important role in the maintenance of muscle cell homeostasis." (PMID 31481932, 2019). "In addition to muscle atrophy, we also observed a marked increase in proteins associated with myopathies and neurodegenerative diseases, such as VCP, TDP-43 and FUS/TLS, within the muscle fibers of Rpt3−/− mice." (PMID 25380823, 2014). "Of the mitochondrial functions downstream of VCP, MERCs are relevant to neurodegenerative diseases in general, and to ALS specifically." (PMID 38891822, 2024). "In particular, p97/VCP is involved in protein degradation via autophagy, a pathway found dysfunctional in many degenerative diseases, including myopathies." (PMID 37602234, 2023). "The regulation of ubiquitination by VCP/p97 governs cellular physiology and is relevant in various cancers and degenerative diseases." (PMID 32716961, 2020). "mTORC1 signaling is also disrupted by mutations in p97 (also called VCP or cdcD, referred to as human p97; hp97), an evolutionarily conserved AAA ATPase, contributing to the pathogenesis of degenerative diseases." (PMID 32879008, 2020). "Taken together, our data establish a functional link between lysosome tubule dysfunction and the pathology of VCP-related degenerative diseases." (PMID 26167652, 2015). "The dynamics and integrity of this tubular lysosomal network requires VCP, an AAA-ATPase that, when mutated, causes degenerative diseases of muscle, bone and neurons." (PMID 26167652, 2015). "The genetic link between VCP missense mutations and a hereditary disorder, first discovered in IBMPFD, has recently been extended to other degenerative diseases, although the underlying pathogenic mechanism remains elusive." (PMID 25255315, 2014). "To date, there is no unifying concept that describes the role of VCP mutations in neurodegenerative diseases." (PMID 37545006, 2023). "VCP/p97 is an attractive therapeutic target for cancer and neurodegenerative diseases." (PMID 28322292, 2017). "Moreover, age-related changes in VCP levels are known to induce chronic inflammation, pathogenesis of neurodegenerative diseases and cataract." (PMID 21085581, 2010). "Thus, this mode of VCP activation may be a very attractive target for many neurodegenerative diseases." (PMID 35842429, 2022). "Additionally, the CC repeat region of all IQGAPs isoforms stimulates neural development and spine morphogenesis via interaction with valosin containing protein (VCP) which also suggests a crucial role of IQGAPs in the pathophysiology of neurodegenerative diseases." (PMID 35785216, 2022). "Additionally, the protein VCP, involved in various neurodegenerative diseases, including HSP, is necessary for autophagosome maturation in basal autophagy and proteasome-inhibition conditions, in addition to its role in conjunction with strumpellin (SPG8) in endocytosis." (PMID 34359848, 2021). "SS + RSD mice show enrichment for genes related to neurodegenerative disease processes (CTNNB1, CSF1R, VCP), while sirtuins, which prevent aging and neurocognitive diseases, were less enriched." (PMID 39629138, 2024). "Several VCP disease mutations block the VCP-SVIP interaction and also engender TL network collapse and autophagic dysfunction, indicating that loss of this lysosome morphology may underlie some aspects of degenerative disease pathology, perhaps in association with defective autophagy." (PMID 35646899, 2022). "Genes that contribute to FTD include: C9ORF72, FUS, VCP, TDP–43, MAPT/tau, CHMP2B, PGRN, TBK1, and TMEM106B, thus there is overlap with other neurodegenerative diseases including: ALS (C9ORF72, FUS, VCP and TDP–43), AD (tau) and PD (tau)." (PMID 32357532, 2020).
neurodegenerative disease (continued). "Also, mutations in the valosin-containing protein (VCP) gene, associated with clearance of stress granules, cause autosomal dominantly inherited ALS15, 16 suggesting that disturbances in RNA metabolism and SG dynamics are involved in the pathogenesis of neurodegenerative diseases." (PMID 27460788, 2016). "Valosin-containing protein (VCP), a ubiquitin-selective partner protein, participates in the autophagic regulation of stress granule (SG) morphology and composition by interacting with lysosomes in neurodegenerative diseases." (PMID 34937577, 2021). "Given the prevalence of dendritic pathology in neurodegenerative diseases, further study of these processes may offer important insights regarding how PINK1 and VCP function to prevent neurodegeneration." (PMID 30783609, 2018). "Future analyses of the interactomes of wild-type and mutant SQSTM1, TBK1 and VCP are needed to pinpoint how these proteins cooperate in a common complex with OPTN and UBQLN2 and how alterations in this complex may lead to ALS or other neurodegenerative diseases." (PMID 27164932, 2016).
tumor (61 papers, 2008 to 2026). "The six‐gene diagnostic model (AIFM2, ABCG1, LIPG, DGAT2, LPCAT1, and VCP) demonstrated near‐perfect classification of tumor versus normal tissues (AUC ≈0.99 in ROC analysis; 99.8% accuracy in SVM analysis)." (PMID 40804485, 2025). "p97/VCP, which is associated with tumor invasion and metastasis, plays a role in regulating the activity of nuclear factor κB." (PMID 37374283, 2023). "We found that VCP expression is significantly increased in tumor tissues and is associated with advanced TNM stages and poorer prognosis in HCC patients." (PMID 35562734, 2022). "The results indicated that the up-regulated VCP expression was significantly associated with the advanced tumor-node-metastasis (TNM) stage (P-value = 0.03)." (PMID 35562734, 2022). "The results indicated the up-regulation of mTOR signaling pathway in the group with high VCP expression, which is known to associate with tumor progression." (PMID 35562734, 2022). "The overexpression of Pbx2 is associated with tumor size, stage, and metastasis, as well as a high expression of the valosin-containing protein (VCP) in GSCC cells." (PMID 33402862, 2020). "Next, we tested if VCP/p97 expression is linked to metabolic pathways in purified bone marrow tumour cells of 261 patients with MM." (PMID 30626938, 2019). "Furthermore, VCP was reported to be one of the few known recurrent amplicons at the DNA level associated with tumor metastasis, which is probably related to nuclear factor kappa B (NF-κB) signaling pathway." (PMID 34917511, 2021). "In addition, the inhibition of miR-198 leads to the upregulation of Pbx-1 and VCP, which causes tumor progression." (PMID 33402862, 2020). "Finally, we observed inactivating mutations in VCP in tumor samples reported by the Cancer Genome Atlas (TCGA) sequencing studies." (PMID 29367883, 2017). "Given that tumours may be hyperdependent on nutrient supplies and may scavenge extracellular protein to ensure sufficient amino acid availability, the VCP inhibitor-associated heightened dependence on amino acid supplies may be clinically relevant." (PMID 26720340, 2015). "Recent evidence also suggested that VCP and/or its associated co-factors are also implicated in the direct regulation of HIF1α (hypoxia-inducible factor 1α; tumor angiogenesis and metastasis promoter), Nrf2 and Aurora B kinase (implicated in genomic instability)." (PMID 22216170, 2011). "Moreover, this study identified VCP as one of the few known recurrent amplicons at the DNA level associated with tumor metastasis." (PMID 22216170, 2011). "We found that overexpression of VCP could rescue tumor growth inhibition caused by USP11 knockdown." (PMID 33758608, 2021). "As with Cal-27 tumor cell lines, each candidate gene caused a significant increase in the proliferation of the candidate gene expressing cell lines compared to the empty vector control cell line (VCP: P = 1.34 × 10−4, DCTN3: P = 1.16 × 10−4, STOML2: P = 2.14 × 10−5)." (PMID 25060540, 2014). "Significantly, upon immunodepletion of CD8+T cells, development suppression of tumors with Vcp depletion in immunocompetent mice was nearly abolished, underscoring the vital importance of effector CD8+T cells in VCP-mediated tumor growth." (PMID 39848960, 2025). "Valosin-containing protein (VCP/p97) is a key regulator of proteostasis and cellular stress response and has been linked to tumor progression and poor prognosis in various malignant diseases." (PMID 41357812, 2025). "Next we validated the metabolomics results, G3P levels decreased both inside and outside the cells of human and mouse origin in VCP depleted cells, and also increased markedly in conditioned medium produced by tumor cells." (PMID 39848960, 2025). "C1QL1 interacts with HSP90α and VCP and executes a tumor-suppressive function by enhancing the proteasomal degradation of HSP90α and VCP, consequently leading to ERS/UPR-related caspase-dependent apoptosis." (PMID 40583061, 2025).
tumor (continued). "Collectively, the findings indicate that VCP in tumors hinders the anti-tumor capabilities of effector CD8+T cells within TME, thereby facilitating the HCC progression." (PMID 39848960, 2025). "This demonstrates that targeted delivery can rescue VCP inhibitors—abandoned after CB clinical failure due to off-target toxicity —by fundamentally altering the biodistribution to achieve tumor selectivity." (PMID 41304839, 2025). "This strategy, involving the inhibition of VCP to regulate G3P levels, provides new theoretical support for tumor immunotherapy and key clues for developing more effective treatment methods." (PMID 39848960, 2025). "As a matter of fact, inhibition of Ter94/VCP is considered to be a promising strategy for tumor intervention." (PMID 38710747, 2024). "VCP organized enhancer-promoter interactions and supported oncogenic gene expression, and pharmacological inhibition of VCP repressed xenograft tumor growth, presenting a potential new therapeutic avenue." (PMID 38916046, 2024). "In contrast, various VCP inhibitors have demonstrated potent anti-tumor activities across various hematologic and solid tumor models." (PMID 38218922, 2024). "CB-5083, a VCP inhibitor with high specificity for the D2 domain, has demonstrated good solubility, oral bioavailability, and high uptake in tumor tissues." (PMID 39489738, 2024). "We have previously found that miR-198 acts as a tumor suppressor in PDAC through the targeting of factors including Valosin-containing protein (VCP)." (PMID 37631252, 2023). "A therapeutic regimen using LPNP-p198 followed by gemcitabine thereby effectively inhibits tumor cell proliferation and induces tumor cell apoptosis in an orthotopic PDAC mouse model through miR-198-mediated VCP regulation." (PMID 37631252, 2023). "We have shown therapeutic delivery of miR-198 using LGA-PEI as a delivery system resulted in repression of VCP-associated autophagy and sensitized PDAC to gemcitabine treatment, reducing tumor burden and metastatic spread in PDAC mouse models." (PMID 37631252, 2023). "Further analysis of the difference in VCP expression between tumor and adjacent normal tissues was conducted in the HCC cohort from TCGA, and consistent results were obtained." (PMID 35562734, 2022). "Valosin-containing protein (VCP) is a member of the AAA-ATPase family associated with multiple molecular functions and involved in tumor metastasis and prognosis." (PMID 35562734, 2022). "The results revealed that tumor growth rate was significantly accelerated in the group overexpressing VCP." (PMID 35562734, 2022). "Data analysis using the GEO database showed that VCP expression was significantly increased in tumor samples compared to the corresponding normal tissue samples." (PMID 35562734, 2022). "The D1 domain of VCP and A box of HMGB1 were identified as the critical regions for their interaction, and D1 area was required for the tumor-promoting effects induced by VCP expression." (PMID 35562734, 2022). "In vivo studies indicated that up-regulated VCP expression accelerated tumor growth in a subcutaneous HCC model." (PMID 35562734, 2022). "We performed IHC staining on the tumor to look for increased VCP expression in comparison to normal peripheral nerve tissue." (PMID 35841038, 2022). "We performed IHC staining on the tumor and compared VCP expression in the tumor versus normal frontal cortex tissue." (PMID 35841038, 2022). "The results of IHC staining indicated the markedly increased VCP expression in tumor tissues compared to the adjacent normal tissues." (PMID 35562734, 2022). "Higher VCP/p97 levels correlated with a high invasion depth (T3–4), the presence of venous invasion and advanced tumor stage (III and IV)." (PMID 34576340, 2021). "Another study suggested the interaction of EPSTI1 with valosin-containing protein (VCP) and the subsequent activation of NF-κB signaling contributed to the increased tumor invasion and metastasis." (PMID 33970103, 2021).